BCL2 (BCL2 apoptosis regulator)
Diseases named in the same sentence as BCL2 in open-access papers (continued):
Sharing a sentence is not in itself a finding about the gene and the disease.
nephritis (3 papers, 2016 to 2024). Inflammation of renal tissue. "One or more of these protein expressions may be considered as possible nephritis flare biomarkers, mainly Bcl-2 that had the lowest proportion in patients with positive anti-dsDNA." (PMID 38562920, 2024). "In this regard, our group demonstrated that patients with jSLE have altered expressions of the apoptosis-related proteins Fas and Bcl-2 in lymphocytes and monocytes, as well as altered sFas, sTRAIL, sFasL, and sMer levels, which related to disease activity and/or nephritis." (PMID 38562920, 2024). "Reduced TRAIL, Bcl-2, TNFR1, and Fas expressions occurred in patients with nephritis." (PMID 38562920, 2024). "Patients with jSLE without nephritis had significantly reduced proportion of Bcl-2–expressing NK cells [median: 70.7% (range: 5.0–95.8) vs. median: 94.8% (range: 87.6–100.0), p = 0.04] when compared to healthy controls." (PMID 38562920, 2024). "This study extends to NK cells an altered profile of TRAIL, Bcl-2, TNFR1, Fas, FasL, Bax, Bim, and caspase-3 proteins in patients with jSLE, particularly in those with active disease, positive anti-dsDNA, nephritis, and without neuropsychiatric involvement." (PMID 38562920, 2024).
nodular fasciitis (3 papers, 2016 to 2025). A self-limiting, rapidly growing, non-encapsulated benign neoplasm that arises from the soft tissues. "In other cases, such as desmoids tumors and nodular fasciitis, BCL2 reactivity was also consistently negative in tumor cells, with BCL2 reactivity only in scattered small lymphocytes." (PMID 34572445, 2021).
oral cavity cancer (3 papers, 2017 to 2026). A primary or metastatic malignant neoplasm involving the oral cavity. "In addition, we found a statistically significant association between the anti-apoptotic gene BCL2 SNP and oral cavity cancer susceptibility." (PMID 30959967, 2019).
Osteochondroma (3 papers, 2008 to 2016). A common, benign cartiliginous neoplasm arising from the metaphysis of bone.
pheochromocytoma (3 papers, 2008 to 2022). "Disruption of the interaction between Bcl‐2 and Beclin1 has been implicated in maslinic acid‐promoted autophagy in rat pheochromocytoma cells." (PMID 32239627, 2020).
phyllodes tumor (3 papers, 2014 to 2024). A benign, borderline, or malignant fibroepithelial neoplasm arising from the breast and rarely the prostate gland. "The expression of CD34 and Bcl-2, which is generally seen in malignant phyllodes tumors and periductal stromal sarcomas, has not been observed in this case." (PMID 25309767, 2014). "IHC may show expression of CD10, but phyllodes tumors generally express CD34 and B-cell lymphoma 2 (bcl-2) and do not express cyclin D1." (PMID 39474112, 2024).
primary effusion lymphoma (3 papers, 2021 to 2023). A large B-cell lymphoma located in the body cavities, characterized by pleural, peritoneal, and pericardial fluid lymphomatous effusions and that is always associated with human herpes virus-8 (HHV-8). "Activation of JNK1 leads to Bcl‐2 phosphorylation and autophagy in primary effusion lymphoma." (PMID 33570213, 2021).
pterygium (3 papers, 2011 to 2023). A wedge-shaped fibrovascular lesion arising from the bulbar conjunctiva and extending to the cornea. "Western blot analysis revealed that Bcl-2 siRNA significantly inhibited Bcl-2 expression in pterygium epithelial cells." (PMID 28779179, 2017). "We next examined the exact relationship between autophagy and apoptosis by transfecting pterygium epithelial cells with Bcl-2 siRNA (50 nmol/l, 48 hours)." (PMID 28779179, 2017). "mTORC1 activation inhibits apoptosis in pterygium by regulating Beclin 1-dependent autophagy via targeting Bcl-2." (PMID 28779179, 2017). "Activated autophagy with increased Beclin 1 expression was observed when Bcl-2 was silenced by siRNA in cultured pterygium epithelial cells." (PMID 28779179, 2017). "In this study, we tested the expression of two proliferation markers (PCNA and Ki-67) and four apoptosis-related bio-markers (mP53, Bcl-2, Bax, and caspase-3) in pterygium and normal conjunctiva samples." (PMID 21738398, 2011). "In the molecules involved in apoptosis, the results showed that the positive rate of Bcl-2 and mP53 significantly increased in the pterygium samples." (PMID 21738398, 2011). "The results showed that positive-PCNA, mP53, and Bcl-2 rates were significantly increased in the pterygium samples compared to normal conjunctiva samples." (PMID 21738398, 2011). "In our study, Bcl-2 was expressed in the epithelial layer of all the pterygium samples and two of the normal conjunctiva samples." (PMID 21738398, 2011). "Bcl-2 was expressed in the epithelial layer of all the pterygium samples and in two normal conjunctiva samples." (PMID 21738398, 2011). "As a matter of fact, this hypothesis in pterygium has been supported by the finding of BCL-2 overexpression." (PMID 36901760, 2023). "Interestingly, rapamycin treatment not only rescued LC3 expression in pterygium epithelial cells but also downregulated Bcl-2 expression." (PMID 28779179, 2017). "Interestingly, rapamycin rescued the inhibition of autophagy and the increased expression of Bcl-2 in cultured pterygium epithelial cells." (PMID 28779179, 2017). "In the present study, we found that autophagy is strongly inhibited in pterygium compared with normal conjunctiva and that autophagy is significantly inversely correlated with the expression of Bcl-2, an anti-apoptotic member of the Bcl-2 family that is involved in cell survival." (PMID 28779179, 2017). "Immunochemical staining showed that Bcl-2-positive cells were nearly undetectable in normal conjunctiva, but were significantly increased and expressed across the entire width of the epithelial layer in pterygium when the epithelial hyperplasia was florid." (PMID 28779179, 2017). "The Bcl-2-positive rate was significantly higher in the pterygium samples (p=0.000)." (PMID 21738398, 2011). "Our results demonstrated that the negative effect of activated mTORC1 in the apoptosis of pterygium epithelial cells occurs, at least in part, through the inhibition of Beclin 1-dependent autophagy by targeting Bcl-2." (PMID 28779179, 2017).
rectal adenocarcinoma (3 papers, 2012 to 2023). "This is the case for rectum adenocarcinoma: its five oncogenes are BCL2, KIT, KLF4, MET, and PDGFRA." (PMID 31900418, 2020). "Most commonly gained or lost genes seen in rectal adenocarcinoma (FLT3, CDX2, GNAS, BCL2, SMAD4, MALT1) are not found in rectal squamous cell carcinoma." (PMID 36357817, 2023).
renal hypoplasia (3 papers, 2015 to 2022). Renal hypoplasia is a developmental anomaly in which one or both kidneys (unilateral or bilateral renal hypoplasia, respectively) have a deficit in the number of nephrons and may be small. "It acts in opposition to Bcl-2, such that removal of a single Bim allele is sufficient to prevent renal hypoplasia/cystic dysplasia in Bcl-2 −/− mice." (PMID 36139134, 2022). "Moreover, similar to papillorenal syndrome, mice globally lacking Bcl-2 expression exhibit renal hypoplasia in part due to decreased distance of the first ureteric bud branch point and subsequent reduced ureteric bud branching." (PMID 36139134, 2022).
Richter syndrome (3 papers, 2022 to 2024). Transformation of chronic lymphocytic leukemia into aggressive non-Hodgkin's lymphoma, usually diffuse large B-cell lymphoma (immunoblastic or centroblastic variant). "Interestingly, all studies that investigated combined BCL-2 and PI3K inhibition related a major part of the synergistic activity to the diminished expression levels of the anti-apoptotic proteins MCL-1 or BCL-xL irrespective of the hematological neoplasm (DLBCL, Richter’s syndrome, NHL, and AML)." (PMID 36674872, 2023).
SARS-CoV infection (3 papers, 2010 to 2022). "SARS-CoV infection can downregulate Bcl-2 and upregulate Bax, inducing apoptosis via the mitochondrial signaling pathway." (PMID 36560727, 2022). "Regarding the human coronaviruses, ex-vivo experiments have demonstrated that upon SARS-CoV infection, viral 7a protein directly interacts and forms a complex with antiapoptotic Bcl-XL protein and other prosurvival factors (Bcl-2, Mcl-1, and A1), promoting apoptosis in a caspase-3 dependent manner." (PMID 33652685, 2021). "Anti-apoptotic Bcl-2 protein inhibits caspase-dependent apoptosis induced by SARS-CoV infection but does not affect viral replication kinetics." (PMID 20144233, 2010).
serous ovarian tumors (3 papers, 2012 to 2020). "To reassociate these molecular findings with clinical findings, we produced an unrelated patient dataset, in which we quantified BCL2 protein levels in FFPE specimens of high-grade serous ovarian tumors." (PMID 31044156, 2019). "Thus, they have suggested that bcl-2 could be specific for serous tumors and might be related with ovarian serous tumor pathogenesis." (PMID 22995373, 2012).
Shock (3 papers, 2010 to 2019). The state in which profound and widespread reduction of effective tissue perfusion leads first to reversible, and then if prolonged, to irreversible cellular injury. "Alam and colleagues have shown that valproate treatment enhances survival following lethal hemorrhagic shock with and without polytrauma (300 and 400 mg/kg, respectively), and that this protection is associated with nuclear translocation of ß-catenin and increased expression of bcl-2." (PMID 20614021, 2010).
silicosis (3 papers, 2021 to 2025). Silicosis is a respiratory disease caused by breathing in (inhaling) silica dust. "Western blot analysis detected apoptosis-related proteins, the results indicated that the anti-apoptotic protein Bcl-2 was inhibited in silicosis (p = 0.005, 95%CI = 0.20–0.31), while the pro-apoptotic protein was activated (p = 0.016, 95%CI = −0.08 to −0.02)." (PMID 41561355, 2025). "We observed a lower proportion of α-SMA+ myofibroblasts with coexpression of BCL-2 in patients with silicosis compared with those with IPF." (PMID 36752201, 2023). "Our previous study had found that the decreased ratio of Bcl-2/Bax resulted in the caspase-3 activation in the silicosis mice model." (PMID 34360876, 2021). "MiR-449a induced autophagy activity and reduced Bcl-2 level in silica-activated fibroblasts or a silicosis mice model." (PMID 34360876, 2021).
Sjögren syndrome (3 papers, 2022 to 2025). "NHL and Sjögren’s syndromeBCL2 (NHL) and IRF5 (Sjögren’s Syndrome) a potential cross-pathway interaction is suggested by the connection between BCL2’s role in apoptotic control in NHL and IRF5’s role in the immunological response in Sjögren’s syndrome." (PMID 40321894, 2025). "Some putative discrepancies, such as the expression of Bcl-2 in Sjögren’s syndrome, are the result of different methodical approaches (e.g., serum and salivary glands versus peripheral blood cells)." (PMID 37353767, 2023).
small cell carcinoma (3 papers, 2018 to 2024). A neuroendocrine carcinoma composed of small malignant cells which are often said to resemble "oat cells" under the microscope. "Immunohistochemical analysis of BCL2 revealed that it was upregulated in most small cell carcinomas." (PMID 38326851, 2024). "The 5 tumors with the highest BCL2 protein expression had concurrent expression of at least 1 neuroendocrine marker; 3 were identified as small-cell carcinomas and 2 as large-cell neuroendocrine carcinomas." (PMID 39286979, 2024). "Biopsy specimen stained positive for CK, CD56, NSE, BcL2, Synaptophysin, PAX-5, and TTF-1, but negative for Chromogranin, CD57, and NFP; consistent with small cell carcinoma." (PMID 30428872, 2018).
soft tissue tumors (3 papers, 2021 to 2025). "□ Synovial Sarcoma: Most cases express CD99, BCL-2, and TLE1 proteins, with molecular genetic analysis serving as a critical tool for distinguishing it from other soft tissue tumors." (PMID 40308487, 2025). "Additionally, various molecular markers, such as CD99, BCL-2, and EMA, may help differentiate SS from other soft tissue tumours." (PMID 40391194, 2025).
status epilepticus (3 papers, 2012 to 2023). Status epilepticus is defined as a continuous seizure lasting more than 30 min, or two or more seizures without full recovery of consciousness between any of them. "Oxidized protein level, translocation of Bcl-2, Bax and cytochrome c between cytosol and mitochondria, and expression of peroxisome proliferator-activated receptors γ (PPARγ) and UCP2 were examined in the hippocampal CA3 subfield following KA-induced status epilepticus." (PMID 22849356, 2012).
teratoma (3 papers, 2015 to 2023). A non-seminomatous germ cell tumor characterized by the presence of various tissues which correspond to the different germinal layers (endoderm, mesoderm, and ectoderm). "The histological analysis results showed that there were glands (endoderm), muscles (mesoderm), and neural tube tissues (ectoderm) in the teratoma from BCL2‐OE haESCs, suggesting that BCL2‐OE haESCs had the potential to differentiate into three germ layers." (PMID 37144356, 2023). "In addition, BCL2‐OE haESCs can contribute to normal chimeric embryos at E10.5 and differentiate into a 21‐day teratoma with a very high proportion of haploid cells." (PMID 37144356, 2023). "Here, we show that overexpression (OE) of an antiapoptosis gene, BCL2, in haESCs robustly ensures their haploidy maintenance in various situations, even under strict differentiation in vivo (embryonic 10.5 chimeric fetus or 21‐day teratoma)." (PMID 37144356, 2023). "Similarly, teratomas develop in mice overexpressing the anti-apoptotic factor Bcl2 but not in mice null for Bax, a pro-apoptotic factor analogous to Bcl2." (PMID 26176933, 2015). "Interestingly, 19.4% of the GFP‐negative cells from the BCL2‐OE teratoma were also at the 1n peak." (PMID 37144356, 2023). "To assess the pluripotency of BCL2‐OE haESCs to three germ layers, we subcutaneously injected approximately 1 × 107 cells into the limb of a 6‐week‐old male SCID mouse to form teratomas." (PMID 37144356, 2023). "Genomic PCR showed that the PB was still in the GFP‐negative cells from the BCL2‐OE teratoma, whereas they no longer expressed BCL2 and GFP." (PMID 37144356, 2023).
tongue squamous cell carcinoma (3 papers, 2019 to 2024). A squamous cell carcinoma that arises from the tongue. "PAIP1 knockdown could decrease the expression of Ki67 and Pcna, and increased Bax/Bcl2 index and caspase-3 expression in human tongue squamous cell carcinoma." (PMID 37101794, 2023).
Tumor Lysis Syndrome (3 papers, 2016 to 2022). a group of metabolic abnormalities that can occur as a complication during the treatment of cancer, most commonly after the treatment of lymphomas and leukemias. "The initial clinical trials of the BCL-2 inhibitor venetoclax in AML were focused on dose finding, in light of the uncertain risk/benefit profile associated with tumor lysis syndrome (TLS), as well as on obtaining a preliminary assessment of the clinical efficacy of the drug." (PMID 30972300, 2019).
Ureteral obstruction (3 papers, 2019 to 2022). Obstruction of the flow of urine through the ureter. "Bcl-2 is an anti-apoptotic gene that has an inverse correlation with Bax, as shown in the previous study of unilateral ureteral obstruction (UUO) subjects, whereby it was shown that Bcl-2 levels will decrease during UUO." (PMID 36699321, 2022). "Bcl-2 expression was strong in mildly dilated tubules and weak in severely dilated tubules of rats with ureteral obstruction." (PMID 36699321, 2022). "Apoptosis of renal tubular epithelial cells after ureteral obstruction could be reduced by regulating Bax and bcl-2." (PMID 32917204, 2020). "Following unilateral ureteral obstruction (UUO) for 2 weeks, expression of the GPR40 protein was significantly decreased, while the Bax/Bcl-2 protein ratio was increased in the obstructed kidney compared with that in the control." (PMID 31295865, 2019).
vitiligo (3 papers, 2012 to 2022). Generalized well circumscribed patches of leukoderma that are generally distributed over symmetric body locations and is due to autoimmune destruction of melanocytes. "It was reported that a lower ratio of Bcl-2/Bax was detected in perilesional melanocytes as compared to the control melanocytes, which signifies that altered expression of Bcl-2 and Bax might render melanocytes from vitiligo patients susceptible to the induction of apoptosis." (PMID 35103096, 2022). "Moreover, Baicalein, an antioxidant that proved beneficial to patients with vitiligo, was found to protect melanocytes by reducing the release of Cyt C, the Bax/Bcl-2 ratio, and caspase-3 level in a concentration-dependent manner in vitro." (PMID 35103096, 2022). "The mechanism of apoptosis was also indicated by decreased levels of anti-apoptotic protein Bcl2 in lesional skin compared to nonlesional skin of vitiligo patients." (PMID 22500953, 2012). "Our study suggests that downregulation of FADS1 in vitiligo melanocytes could be a critical determinant for apoptosis, since its suppression in normal PIG1 cells triggers apoptosis by increasing ROS generation as well as expression of Bax and active caspases 3 and 9, while downregulating Bcl-2." (PMID 31866583, 2019).
adenosquamous carcinoma (2 papers, 2010 to 2013). A carcinoma composed of malignant glandular cells and malignant squamous cells. "The co-methylation of SIX6 and SOX1, or the co-methyaltion of SIX6, RARB and SOX1 was associated with adenosquamous carcinoma (ADC), and the co-methylation of BCL2, RARB and SIX6 was associated with smoking." (PMID 23599765, 2013).
Age-related cataract (2 papers, 2019 to 2023). A type of cataract (opacification of the lens) that forms during the course of aging. "miR-181 was highly expressed in the lens tissue of age-related cataract and negatively regulates Bcl-2, thereby inhibiting the proliferation of lens epithelial cells." (PMID 36644575, 2023). "A novel mechanism of microRNA-15a/BCL2/E2F3 axis in age-related cataracts was revealed in our present study." (PMID 31737898, 2019). "In summary, the results of our present study demonstrated that microRNA-15a was able to modulate lens epithelial cells apoptosis and proliferation through targeting BCL2 and E2F3 in age-related cataracts." (PMID 31737898, 2019).